PMS2 (PMS1 homolog 2, mismatch repair system component)
Diseases named in the same sentence as PMS2 in open-access papers (continued):
Sharing a sentence is not in itself a finding about the gene and the disease.
lymphoma (6 papers, 2015 to 2025). A malignant (clonal) proliferation of B- lymphocytes or T- lymphocytes which involves the lymph nodes, bone marrow and/or extranodal sites. "Therefore, our finding of PMS2 mutation among CVID patients with lymphoma corresponds well with these reports." (PMID 30723478, 2018). "Additional eight mutations that were significantly enriched in rHL/prHL affect genes that were previously associated with the progression of other lymphoma subtypes (e.g., PDGFRB, KAT6A, HGF, EPHB1, NSD2, PMS2)." (PMID 39992429, 2025). "In addition, the expression levels of PMS2 tended to be lower in the lymphoma group than in the BLV-infected cattle groups." (PMID 33143351, 2020). "In addition, MSH6 and PMS2 tended to be lower in BLV-infected cattle with lymphoma compared within infected cattle." (PMID 33143351, 2020).
rectal tumor (6 papers, 2007 to 2026).
small bowel cancer (6 papers, 2021 to 2022).
hereditary colorectal cancer (5 papers, 2014 to 2026). "In a patient with multiple CAA, hereditary colorectal cancer, transcobalamin II deficiency, agenesis of the corpus callosum and mental retardation, a germline mutation of the PMS2 gene was found." (PMID 25997068, 2015).
thyroid cancer (5 papers, 2021 to 2024). "DriverML predicted that BRAF and NF1/PMS2 mutations are the main driving mutations in thyroid cancer, and they play a certain role in regulating its development." (PMID 35865459, 2022). "Because BRAF and NF1/PMS2 have significant mutually exclusive relationship, we speculate that the mechanism of gene mutation leading to the occurrence and development of thyroid cancer may be different between the two groups." (PMID 35865459, 2022). "Using a computer algorithm to identify major driver mechanisms in our PTC cohort, the results showed that, in addition to BRAF mutations, NF1, PMS2, CDC27 and PPP4R2 gene mutations are also involved in the development of thyroid cancer, and joint mutations often occur." (PMID 35865459, 2022).
Turcot syndrome (5 papers, 2009 to 2017). "We have previously reported a homozygous carrier of PMS2 c.989-1G > T with Turcot syndrome." (PMID 24790682, 2014).
uterine cancer (5 papers, 2021 to 2025). Primary or metastatic malignant neoplasm involving the uterine corpus and/or the cervix.
cholangiocarcinoma (4 papers, 2019 to 2026). A carcinoma that arises from the intrahepatic biliary tree (intrahepatic cholangiocarcinoma) or from the junction, or adjacent to the junction, of the right and left hepatic ducts (hilar cholangiocarcinoma). "A cholangiocarcinoma patient with insufficient tumour tissue had a microsatellite unstable tumour based on testing of circulating tumour DNA which revealed a concomitant PMS2 mutation." (PMID 41231502, 2026). "The query revealed six Subjects (Subject 5 - Subject 10) positive for germline VUS in PMS2 or MSH6 genes who had non-Lynch related tumors of cholangiocarcinoma, lung adenocarcinoma, clear cell renal cell carcinoma, serous type endometrial adenocarcinoma, and urothelial carcinoma." (PMID 36091175, 2022).
endometrioid adenocarcinoma (4 papers, 2017 to 2024). An adenocarcinoma characterized by the presence of malignant glandular epithelial cells resembling endometrial cells. "Of six MLH1/PMS2–deficient grade III endometrioid adenocarcinomas, PD-L1 was expressed in four (66.7%)." (PMID 34685418, 2021). "We further examined the small subset of MLH1/PMS2–deficient grade III endometrioid adenocarcinomas and found that PD-L1 was expressed in the majority." (PMID 34685418, 2021). "In conclusion, tumors with MLH1/PMS2 loss and high-grade endometrioid adenocarcinomas were more likely to express PD-L1 in tumor cells." (PMID 34685418, 2021). "Further, we measured the frequency of PD-L1 expression in six MLH1/PMS2–deficient grade III endometrioid adenocarcinomas and found that PD-L1 was expressed in four (66.7%)." (PMID 34685418, 2021). "Tumors with MLH1/PMS2 loss (23.8% of all tumors in our sample) and high-grade endometrioid adenocarcinomas (13.5% of all endometrioid adenocarcinomas in our sample) were more likely to express PD-L1 in tumor cells." (PMID 34685418, 2021). "To explain the heterogeneity of results, we hypothesized that the relationship between the FIGO grade of endometrioid adenocarcinomas and PD-L1 expression may be mediated by MLH1/PMS2 loss because MMR deficiency is common in high-grade endometrioid adenocarcinomas." (PMID 34685418, 2021).
Ewing sarcoma (4 papers, 2016 to 2023). A small round cell tumor that lacks morphologic, immunohistochemical, and electron microscopic evidence of neuroectodermal differentiation.
Huntington disease (4 papers, 2019 to 2025). Huntington disease (HD) is a rare neurodegenerative disorder of the central nervous system characterized by unwanted choreatic movements, behavioral and psychiatric disturbances and dementia. "Genome wide association studies (GWAS) have shown that PMS2 is a modifier of age at onset and risk of somatic expansion in Huntington’s disease (HD), a CAG-repeat expansion disorder." (PMID 39185211, 2025). "These regions harbor or lie adjacent to MSH3 and PMS2, the genes that were recently implicated in modifying age at onset in Huntington’s disease, likely through a common pathway influencing repeat instability." (PMID 34050153, 2021). "A total of five Huntington’s disease modifier genes (FAN1, MLH1, MSH3, PMS2 and RRM2B) had OMIM phenotype entries, mainly for cancer-related diseases for DNA-repair-related genes." (PMID 39801710, 2025).
osteosarcoma (4 papers, 2022 to 2025). A usually aggressive malignant bone-forming mesenchymal neoplasm, predominantly affecting adolescents and young adults. "Of note, osteosarcoma was recently reported in two patients with CMMRD with compound heterozygous variants in PMS2." (PMID 37308967, 2023). "Analysis of a pediatric osteosarcoma (OS) displayed hypermutation (16.8), alternative lengthening of telomeres (ALT), loss of PMS2 expression in tumor tissue (retained in non-neoplastic cells), PMS2 loss of heterozygosity (LOH), and high-degree of microsatellite instability (MSI) tested by PCR." (PMID 37308967, 2023).
skin cancer (4 papers, 2017 to 2026). "A group of somatic mutations in the PMS2 gene promoter was also identified to 10% of skin cancers and was significantly correlated with an increase in TMB." (PMID 37350936, 2023). "We identify somatically altered genes associated with significantly increased TMB and identify a novel mutation hotspot in the promoter of the PMS2 gene, which is mutated in ~10% of skin cancers and is associated with greatly increased TMB." (PMID 28420421, 2017). "We identify a cluster of somatic mutations in the promoter of the gene PMS2, which occur in 10% of skin cancers and are highly associated with increased TMB." (PMID 28420421, 2017).
squamous cell carcinoma (4 papers, 2017 to 2023). A carcinoma arising from squamous epithelial cells. "Key words:Squamous cell carcinoma, mouth neoplasms, mismatch repair endonuclease PMS2, survival." (PMID 33247565, 2021).
Cecal cancer (3 papers, 2019 to 2022). "To support that an interaction of a constitutional PP defect and a high propensity to MMRd due to the heterozygous germline PMS2 PV determines the siblings’ phenotype, we analyzed the TMB and mutational signatures of the patient’s colon and his sister’s cecum carcinoma by whole-exome sequencing." (PMID 36291559, 2022). "A subject with cecal cancer (case 2) who showed histological signs of partially mucinous differentiation had a pathogenic variant of g.MLH1 c.2041G>A, a high frequency of MSI (5 of 5 markers), repressed MLH1 and PMS2 expression." (PMID 31386297, 2019).
cervical cancer (3 papers, 2010 to 2024). A primary or metastatic malignant neoplasm involving the cervix. "We found significant downregulation of PMS2 in cervical carcinoma, which was negatively associated with phosphorylated GSK-3β (s9)." (PMID 20178594, 2010). "Our results suggested that the downregulation of PMS2 in cervical carcinoma tissues might be associated with pGSK-3β production and GSK-3β inactivation." (PMID 20178594, 2010). "Given that few data are available regarding PMS2 modulation in human cervical carcinoma, investigating the mechanisms underlying the regulation of PMS2 may be essential for understanding the significance of PMS2 in carcinogenesis." (PMID 20178594, 2010). "We therefore concluded that PMS2 upregulation significantly enhanced cisplatin-associated chemosensitivity, which may be useful for the treatment of cervical carcinoma." (PMID 20178594, 2010). "The aim of this study was to determine the expression of PMS2 in cervical carcinoma and evaluate the significance of mismatch repair gene PMS2 regulated by glycogen synthase kinase 3β (GSK-3β) in chemosensitivity." (PMID 20178594, 2010). "To further characterize the importance of PMS2 in improving chemosensitization of cervical carcinoma, we analyzed the effects of PMS2 transfection on apoptosis of HeLa cells induced by cisplatin using flow cytometry." (PMID 20178594, 2010). "In the present study, we found a significant PMS2 downregulation in human cervical carcinoma tissue, similar to the results found in other cancers." (PMID 20178594, 2010). "The decrease of PMS2 activity in tissue and the induction of PMS production in HeLa cells suggested that the PMS2 protein may play a more important role in the development of cervical carcinoma." (PMID 20178594, 2010). "Our results provide the preliminary evidence that GSK-3β stabilized PMS2 production, which may play an important role in the carcinogenesis and chemotherapy of cervical carcinoma." (PMID 20178594, 2010). "We found a significant downregulation of PMS2 in cervical carcinoma comparing to other protein." (PMID 20178594, 2010). "If so, the rapid induction and degradation of PMS2 may be essential in the balance between cell survival and death as a sensor of environmental changes in cervical carcinoma." (PMID 20178594, 2010). "Our results provide the evidence that stabilization of PMS2 production by GSK-3β was important to improve chemosensitization, indicating the significance of GSK-3β-related PMS2 downregulation in the development of cervical carcinoma and in developing a potential strategy for chemotherapy." (PMID 20178594, 2010). "Expression of the MMR proteins MLH-1, PMS-2, MSH-2, and MSH-6 was investigated by immunohistochemical staining in a prospectively collected cervical cancer cohort (n=508) with corresponding clinicopathological and follow-up data." (PMID 38950928, 2024).
cervical cancer (continued). "We examined PMS2 and phosphorylated GSK-3β(s9) expression in cervical carcinoma tissues using immunohistochemical staining." (PMID 20178594, 2010).
colorectal adenoma (3 papers, 2019 to 2024). An adenoma that arises from the colon or rectum. "Patient A has removed multiple colorectal adenomas and was recently diagnosed with an MMR-deficient CRC at age 56 (MSI, loss of PMS2 and partial loss of MLH1)." (PMID 36856825, 2023).
endometrial tumor (3 papers, 2007 to 2022). "The endometrial tumor showed BAT26-only instability with a partial loss of MLH1/PMS2 expression and a high PD-L1 combined positive score (CPS = 8)." (PMID 36142641, 2022). "The endometrial tumor showed BAT26-only instability, partial loss of MLH1/PMS2 protein expression, and a high programmed cell death ligand 1 (PD-L1) combined positive score (CPS = 8)." (PMID 36142641, 2022). "In this patient, with an endometrial tumor diagnosed at age 53 and loss of MLH1/PMS2 expression, we identified two variants classified as pathogenic and likely pathogenic in the ATM and ST18 genes, respectively." (PMID 36077770, 2022). "A third MLH1-methylated case carrying only VUS was observed in a patient (ID 828) diagnosed at age 46 with an endometrial tumor, with loss of MLH1/PMS2 expression and a family history of endometrial, prostate and unidentified tumors (mother, father and paternal uncle, respectively)." (PMID 36077770, 2022).
Friedreich ataxia (3 papers, 2012 to 2020). An inherited condition that affects the nervous system and causes movement problems. "Recent studies using Friedreich’s ataxia mouse models have demonstrated that PMS2-deficient mice display an increase in expansion mutations within very long [GAA/TCC] microsatellites." (PMID 23450065, 2013). "Given this unique role, it is tempting to speculate that Pms2 may serve as a genetic modifier of the disease phenotype in Friedreich ataxia." (PMID 23071719, 2012).
gynecological cancer (3 papers, 2017 to 2021). "In contrast, individuals with PMS2 variants have the lowest risk for gynecologic cancer compared with individuals with other LS MMR gene variants." (PMID 34499134, 2021). "The modestly increased risk of CRC and gynecological cancer of PMS2 mutation carriers is not evident before 50 years of age." (PMID 33218006, 2020). "More data are required to extend this recommendation to PMS2 carriers because of their lower gynecological cancer risk, which is not increased before 50 years of age." (PMID 33218006, 2020). "Women with heterozygous PMS2 mutations do not warrant gynecological surveillance because their absolute risk of gynecological cancer is very low." (PMID 28772289, 2017).
hereditary tumor syndrome (3 papers, 2019 to 2023). "Remarkably, 20% (5/24) of the patients with proven hereditary tumor syndrome and isolated loss of PMS2 or MSH6 were microsatellite stable (MSS) by PCR." (PMID 37874379, 2023).